MYCN (MYCN proto-oncogene, bHLH transcription factor)
Diseases named in the same sentence as MYCN in open-access papers (continued):
Sharing a sentence is not in itself a finding about the gene and the disease.
retinoblastoma (continued). "Besides the well-established driver genes RB1 (13q-loss) and MYCN (2p-gain) we identified CRB1 and NEK7 (1q-gain), SOX4 (6p-gain) and NUP205 (7q-gain) as novel retinoblastoma driver candidates." (PMID 27115612, 2016). "MYCN was the most commonly amplified gene in 8.5% (8/94) of tumors in our retinoblastoma cohort." (PMID 24509483, 2014). "One of the goals of our study was to explore the relationship between MYCN amplification and RB1 inactivation to determine if a subset of retinoblastomas can be driven by a single oncogenic lesion (MYCN amplification) without RB1 loss." (PMID 24509483, 2014). "It was proposed that MYCN amplification is sufficient to initiate retinoblastoma in those patients." (PMID 24509483, 2014). "However, one of the challenges with identifying retinoblastomas driven exclusively by MYCN amplification is excluding all possible mechanisms of RB1 gene inactivation including SNVs, indels, LOH, deletions, translocations and promoter hypermethylation." (PMID 24509483, 2014). "In our cohort, we discovered 8 retinoblastomas with MYCN amplification (>10 copies)." (PMID 24509483, 2014). "The authors suggested that in those patients, MYCN amplification may be sufficient for retinoblastoma tumorigenesis." (PMID 24509483, 2014). "Supporting this interpretation, recent studies using MYCN-driven retinoblastoma models have demonstrated that certain retinal progenitor lineages (cone and horizontal progenitors) display relative resistance to apoptosis, thereby facilitating MYCN-mediated tumorigenesis." (PMID 40943594, 2025). "However, a small subset of cases, accounting for approximately 1.5% of all retinoblastomas, is characterized by high-level amplification of the MYCN oncogene without accompanying RB1 mutations." (PMID 40943594, 2025). "In rare cases, sporadic retinoblastoma could develop in the absence of RB1 mutation as a consequence of the somatic amplification of the MYCN gene." (PMID 38398694, 2024). "Knockdown of MYCN in cell models reactivated the differentiated subtype 1 photoreceptor signature, suggesting a transition between the differentiated subtype 1 retinoblastoma and the more aggressive subtype 2 retinoblastoma that can potentially be reversed via targeting MYCN." (PMID 39079981, 2024). "Recently, it has been reported that the amplification of the MYCN gene may cause the development of retinoblastoma even in the absence of RB1 mutations." (PMID 38540335, 2024). "Furthermore, the study provides an explanation to how MYCN may promote proliferation and carcinogenesis in this retinoblastoma model of retinoblastoma tumorigenesis." (PMID 37606819, 2024). "Ceftriaxone, an FDA-approved third generation cephalosporin antibiotic, has been demonstrated with the ability to reduce the volume of unexpected retinoblastoma (RB) with MYCN amplification." (PMID 39594898, 2024). "Additionally, MYCN-driven retinoblastomas are unilateral with an age of onset of about 4.5 months." (PMID 38540335, 2024). "We generated MYCN-knockdown retinoblastoma cell models to assess functional effects and define a MYCN-RB signature, as a potential application to identify patients with retinoblastomas driven by oncogenic MYCN activity who could benefit from MYCN-directed treatment." (PMID 39079981, 2024). "Notably, half of the RB1 wild-type retinoblastoma cases analyzed in this study were characterized by MYCN amplification which was instead absent in most RB1 mutated tumors (97.3%)." (PMID 36982482, 2023). "In addition, amplification of the MYCN oncogene contributes to retinoblastoma." (PMID 35960463, 2022). "Less than 2% of unilateral, non-familial retinoblastoma patients may present with fully functional RB1 but instead with a MYCN oncogene mutation." (PMID 34195690, 2021).
retinoblastoma (continued). "Moreover, it has been observed that, in order to escape apoptosis and further proliferate, retinoblastoma cell proliferation depends on the expression of proteins including RXRγ, MYCN, MDM2, and TRβ2, which are also greatly produced by retinal cone progenitor cells." (PMID 34195690, 2021). "Besides tumor initiation by biallelic loss of the RB1 gene, cytogenetic analysis has identified recurrent copy number variants (CNVs) in retinoblastoma tumors, leading to the proposal of several candidate driver genes other than RB1 such as KIF14, MYCN, DEK, E2F3, RBL2/p130, and NGFR." (PMID 33466343, 2021). "We hypothesize that MYCNOS1 maintains the features of retinoblastoma/cone signature or “stemness” previously reported for MYCNOS234 and that loss of MYCNOS1 expression induces neuronal differentiation in MYCN-amplified retinoblastoma without RB1 mutation." (PMID 33270844, 2020). "MYCNOS appears to play a key role in cancer progression, but whether it acts as a silent passenger or is a pathogenic consequence of MYCN amplification in retinoblastoma is not known." (PMID 33270844, 2020). "Simultaneous expression of MYCNOS with MYCN may be needed to imitate human MYCN-driven retinoblastoma without the loss of RB1 in generating a mouse model." (PMID 33270844, 2020). "Moreover, cooption of MYCN appears instrumental for retinoblastoma tumor growth." (PMID 27296804, 2016). "Moreover, MYCN amplification, a rare feature of most primary human retinoblastomas, occurs with greater incidence in retinoblastomas without RB1 mutations." (PMID 26379276, 2015). "In particular, some participants may not have been familiar with a rare cause of retinoblastoma (amplification of MYCN) and the fact that some unilateral cases of retinoblastoma are heritable." (PMID 26035834, 2015). "In addition, a recent study reported that a small subset of human unilateral nonfamilial retinoblastomas (1.5%) with MYCN amplification (≥10 copies) lack RB1 mutations." (PMID 24509483, 2014). "While RB1 remains the primary gene associated with retinoblastoma, and MYCN amplification accounts for a small subset of non-hereditary, unilateral cases, emerging research has identified a number of additional genes that may play a role in retinoblastoma development or progression." (PMID 41009976, 2025). "However, due to the difficulties in growing retinoblastoma cell lines, a limitation of this study is that further assessments are necessary to conclude whether MYCN protein levels influence the killing effect of complete blockage of the pyrimidine ribonucleotide synthesis pathways." (PMID 38332874, 2024). "Only in our cell models did differences become apparent after MYCN knockdown, when RB1−/− cell lines showed more pronounced expression of the photoreceptor signature than RB1-proficient retinoblastomas." (PMID 39079981, 2024). "In retinoblastoma, MYCN amplification (MYCNA) occurs in RB1−/−MYCNA retinoblastomas and the rare, RB1-proficient MYCNA retinoblastomas." (PMID 39079981, 2024). "DNA methylation and gene expression profiling in further RB1-proficient MYCN-amplified retinoblastomas will help to better characterize differences in molecular circuitry in RB1−/− and RB1-proficient MYCN-amplified retinoblastoma." (PMID 39079981, 2024). "In retinoblastoma, crocin induces apoptosis in Y79 and WERI-RB-1 cell lines with a significant reduction in the expression and stability of the proto-oncogene N-myc (MYCN) protein." (PMID 39334719, 2024). "As we have previously reported, MYCN expression is correlated with immune repression in different tumors, such as SCLC, NB, rhabdomyosarcoma (RMS), retinoblastoma (RB), Wilms’ tumor, T-cell acute lymphoblastic leukemia (T-ALL) and acute myeloid leukemia (ALM)." (PMID 36765949, 2023).
retinoblastoma (continued). "Arguments against this notion are that mice do not develop retinoblastoma with MYCN over-expression unless they also have deficient Rb1 expression and that RB1 functions may be inactivated in the RB1-proficient, MYCNA retina by phosphorylation or by other means than gene mutation." (PMID 35729105, 2022). "In this study, we over-expressed MYCN in the developing chicken retina and in human embryonic stem cell (hESC)-derived retinal organoids to model MYCNA-driven retinoblastoma in RB1+/+ genetic background." (PMID 35729105, 2022). "Furthermore, it can be envisioned that the unique MYCN signature we discovered in these tumors may be explored in the future to adapt a more personalized and targeted approach when treating children with MYCN-amplified retinoblastoma." (PMID 36245757, 2022). "Of the non-RB1 gene alterations in our cohort, only MYCN on 2p24.3 and TSC2 on 16p13.3 correspond with common CNVs that characterize retinoblastoma." (PMID 33466343, 2021). "While retinoblastomas are initiated by genetic alterations in RB1 or, rarely, MYCN, additional somatic changes have been identified that are thought to further drive tumourgenesis." (PMID 33805427, 2021). "Conversely, ectopic overexpression of MYC as well as MYCN induced high-level MDM2 expression and gave rise to rapidly proliferating and MDM2-dependent cone-precursor-derived masses in a cultured retinoblastoma genesis model." (PMID 33425720, 2020). "In studies establishing that MDM2 regulates MYCN in retinoblastoma, we noticed that retinoblastoma cell line RB176 expressed MYC in addition to MYCN." (PMID 33425720, 2020). "MYCN is enriched in human retinoblastoma cells to promote tumor outgrowth, although how MDM2 regulates MYCN is unclear." (PMID 32824373, 2020). "The regulatory specificity was best illustrated in retinoblastoma cell line RB176, in which MYCN and MYC are co-expressed yet MDM2 was needed to sustain only MYCN." (PMID 33425720, 2020). "Besides RB1 mutations, a small proportion of patients (1%) with retinoblastoma may have MYCN amplifications driving their disease, not an RB1 loss of function mutation." (PMID 32633890, 2020). "In another recent publication three retinoblastoma subtypes were compared in human tumors based on RB1 and MYCN; RB1−/−MYCNA, RB1+/−MYCNA, and RB1+/+MYCNA." (PMID 29124525, 2017). "For example, results showed progressive gain of MYCN and E2F3 as well as high expression of p16INK4a and p130 in retinomas compared to a low expression in retinoblastoma." (PMID 29124525, 2017). "Retinoblastoma development is initiated by two sequential hits of RB1 (RB1-/- patients) and in few cases by amplification of MYCN (RB1+/+MYCNA patients)." (PMID 27115612, 2016). "To determine if there was any difference in the molecular features of this retinoblastoma with wild type RB1 and MYCN amplification, we performed gene expression array analysis." (PMID 24509483, 2014). "To characterize the relationship between MYCN amplification and RB1 gene inactivation, we analyzed the RB1 gene status in 46 retinoblastomas with sufficient DNA for custom capture Illumina sequencing." (PMID 24509483, 2014). "Taken together, our data suggest that MYCN and OTX2 are the most common focal gains found in retinoblastoma and RB1, and BCOR are the most common focal losses found in retinoblastoma." (PMID 24509483, 2014). "To identify therapeutic vulnerabilities specific to MYCN-driven retinoblastoma, we assessed drug sensitivity profiles of MYCN-overexpressing cells (MYCNO/E-cells) derived from retinal organoids compared with the established retinoblastoma cell line Y79 (RB1−/−, MYCN-amplified)." (PMID 40943594, 2025). "While 98% of non-heritable retinoblastomas have RB1 mutations, 2% have somatic amplification of the MYCN oncogene without a detectable RB1 mutation." (PMID 41009976, 2025). "Another distinct clinical entity is MYCN-amplified retinoblastoma, which occurs in a few percent of unilateral, non-heritable cases." (PMID 41009976, 2025).
retinoblastoma (continued). "In the case that no methylation is found, test for MYCN gene amplification, which accounts for 1–3% of non-heritable unilateral retinoblastoma cases." (PMID 41009976, 2025). "Additional alterations including reduction in p16INK4B and p130 levels, loss of the tumor suppressor genes CDH11 and p75NTR, and copy number gain and high expression of the oncogenes MYCN, E2F3, DEK, KIF14 and MDM4, can induce clonal expansion and full-blown retinoblastoma." (PMID 40075567, 2025). "Notably, the ectopic expression of MYCN induces MDM2 expression, leading to enhanced proliferation of cone precursor-derived masses in a retinoblastoma genesis model under culture conditions." (PMID 39802403, 2025). "Similarly, retinoblastoma cell proliferation depends on RXRγ, TRβ2, MDM2, and MYCN, implying that intrinsic L/M-cone factors contribute to the oncogenic state." (PMID 40767624, 2025). "A rare form of RB was first reported in 2013, in which high-level amplification of the oncogene MYCN drives tumorigenesis in the absence of pathogenic RB1 mutations (MYCN-amplified, RB1+/+ retinoblastoma)." (PMID 41465072, 2025). "In our cohort of primary retinoblastoma, the MYCN-RB signature generated in the cell line model was able to identify MYCN-driven retinoblastomas with and without MYCNA, which cluster separately based on methylation as cluster C retinoblastomas." (PMID 39079981, 2024). "The MYCN-driven cluster C included not only MYCN-amplified retinoblastomas, but two samples with high MYCN target expression that lacked MYCN amplifications, suggesting alternative ways of activating MYCN-driven tumor progression in retinoblastoma." (PMID 39079981, 2024). "Since no cell lines are derived from subtype 1 retinoblastoma, we explored the functional effects of MYCN in the subtype 2 background by generating MYCN knockdown models from these cell lines." (PMID 39079981, 2024). "MYCN over-expression transforms retinal progenitor cells for cPRs and HCs, implicating the progenitors as the cell-of-origin for this subtype of MYC-induced retinoblastoma in chicken retina and in human retinal organoids." (PMID 35729105, 2022). "About 1–2% of patients with retinoblastoma show no RB1 alteration but instead amplification of MYCN." (PMID 35565295, 2022). "A minority of non-hereditary retinoblastomas (<2%) are initiated by MYCN-amplification without RB1 inactivation." (PMID 34552068, 2021). "Although MYCN amplification in association with RB1 inactivation is known to occur, approximately 2% of retinoblastoma tumors have no derangement in RB1, and reportedly exhibit only MYCN amplification." (PMID 33466343, 2021). "Gains in chromosome 2p involving MYCN were present in 60.9% of our patients, higher than the reported 43% for non-metastatic retinoblastoma with HRPF." (PMID 33567541, 2021). "Moreover, we performed RNA sequencing of five retinoblastoma samples and compared the gene expression of these tumours to normal retinal tissue to find that all cases of retinoblastoma are associated with an increased expression of N-MYC even in the absence of a MYCN genomic abnormality." (PMID 33670346, 2021). "There was no somatic RB1 mutation identified in either the AH or the tumor for any of these cases; on histopathologic review, none of these eyes had characteristic features of primary MYCN amplified retinoblastoma tumors." (PMID 34283049, 2021). "A small subset of patients who develop unilateral retinoblastoma have been found to have MYCN amplification and no RB1 alterations." (PMID 32633890, 2020). "We report that MYC and MYCN show consistently different dependence on MDM2 in cancer cell lines, yet similar abilities to induce MDM2 expression and MDM2-dependent proliferation in the retinoblastoma cell of origin." (PMID 33425720, 2020).
retinoblastoma (continued). "We present two cases of a subtype of retinoblastoma, a rare ocular tumor in children, presenting without the typical mutation in the RB1 gene but showing amplification of the transcription factor MYCN frequently reported in pediatric malignancies." (PMID 32971811, 2020). "A study in mice indicates that there is a limited time window during development where retinoblastoma can develop, and that in adult 3-week-old mice few retinoblastomas emerged when MYCN was overexpressed in retinas lacking RB1." (PMID 29124525, 2017). "This makes inactivation of RB1 by gene mutation or its protein product, pRb, by protein phosphorylation, a necessary condition for initiating retinoblastoma tumorigenesis, independent of MYCN amplification." (PMID 28211617, 2017). "A small, but unique subgroup of retinoblastoma has been identified with no detectable mutation in the retinoblastoma gene (RB1) and with high levels of MYCN gene amplification." (PMID 28211617, 2017). "In addition to the previously reported recurrent focal losses of RB1 and BCOR and amplification of MYCN, we also identified a recurrent focal amplification of OTX2 in 3% of retinoblastomas." (PMID 24509483, 2014). "However, the direct role of none of these genes in retinoblastoma is yet fully understood and warrants further investigation for their potential diagnostic or prognostic relevance; nonetheless, they highlight the expanding genetic landscape of retinoblastoma beyond RB1 and MYCN." (PMID 41009976, 2025). "In rare instances, sporadic retinoblastoma may develop without an RB1 mutation, resulting from somatic amplification of the MYCN gene." (PMID 40317918, 2025). "Furthermore, MYCN overexpression profoundly perturbs critical molecular pathways and the retinal cellular microenvironment, promoting tumor initiation and progression—particularly in RB1-proficient retinoblastoma." (PMID 40943594, 2025). "The 2 retinoblastomas lacking MYCN amplifications had aberrations that could trigger oncogenic MYCN activity through other routes." (PMID 39079981, 2024). "Retinoblastomas lacking MYCN amplifications strongly expressed this gene group (pMYCNnon-A-MYCNAWilcoxon rank sum test = 0.0002623), and expression was highest in cluster A, followed by cluster B (pAC = 0.00058, pBC = 0.00227, pAB = 0.37503; Wilcoxon rank-sum test)." (PMID 39079981, 2024). "In fact, the downregulation of cell cycle G1 to S-phase transition genes such as cyclin kinase inhibitors may promote further proliferation, rather than inhibition, in MYCN-amplified RB1-proficient retinoblastoma." (PMID 36245757, 2022). "IVi pevonedistat, selected as the delivery route because of the low permeability of the drug across the blood–brain barrier, resulted in antitumor effects in in vitro and in vivo preclinical models including MYCN amplified retinoblastomas without evidence of ocular toxicity." (PMID 35433448, 2022). "This study aimed to establish whether the high-level MYCN-amplified, RB1-proficient (MYCNARB1PRO) retinoblastoma present in this cohort displays unique molecular features that discriminate them from the rest of the retinoblastoma genomic subtypes." (PMID 36245757, 2022). "In a small fraction (1.4% of unilateral retinoblastoma) no RB1 mutation was found, but instead an amplification of the MYCN oncogene could be detected and these tumors showed an aggressive clinical course." (PMID 36497295, 2022). "The mouse MYCN-induced Rb1−/− cells were not described as expressing photoreceptor genes in accordance with several mouse retinoblastoma models, including the Rb1−/−Rbl2−/− mice that do not express specific cPR profiles but rather profiles with ACs and HCs, suggesting an alternative cell of origin." (PMID 35729105, 2022). "Retinoblastoma (RB) is an aggressive intraocular malignancy of childhood initiated by biallelic inactivation of the RB1 gene, and a small subset (1–2%) develops with MYCN amplification in the presence of functional RB1." (PMID 36077715, 2022).